CASP2 (caspase 2)
Diseases named in the same sentence as CASP2 in open-access papers (continued):
Sharing a sentence is not in itself a finding about the gene and the disease.
infection (continued). "Thus, the finding that Casp2 and Bcl2 interacted during secondary infection suggests that apoptosis is suppressed during secondary infection, in contrast to the induction of apoptosis during primary infection." (PMID 25341656, 2014). "Several recent studies found that caspase and caspase 4 of F. merguiensis, caspase 2 of L. vannamei and caspase 1 of P. monodon were all up-regulated in the hemocytes after DIV1 infection." (PMID 34512588, 2021). "In this study, we found that CASP2 and PTPN13 were the targets of lncRNAs and down-regulated during infection." (PMID 34130627, 2021). "Additionally, caspase-2, as a member of the caspase family, which is involved in apoptosis, was cleaved and activated in the rat parenchyma at 21 and 28 dpi and in the hippocampus at 14, 21, and 28 dpi, which reveals that obvious apoptosis occurs upon infection with A. cantonensis." (PMID 32038563, 2019). "Infection of macrophages with Brucella abortus activates the NLRP3 inflammasome in a mechanism requiring IRE-1 mediated ER stress, mitochondrial damage and caspase-2 activity." (PMID 28570638, 2017). "The caspase-2 enzyme activity in both RB51- and S2308-infected BMDCs was significantly up-regulated at 1 h, 4 h, and 24 h post infection (P-value <0.05)." (PMID 22927979, 2012). "Various caspases, including the subfamily of inflammatory mediator (CASP1, CASP4), the apoptotic activator (CASP2, CASP8) and the apoptotic executioner (CASP7) were up-regulated in response to infection." (PMID 21110886, 2010). "At 24 h post infection, the number of RB51 surviving inside the macrophages pretreated with the caspase-2 inhibitor was approximately 120 times greater than that inside untreated macrophages." (PMID 19714247, 2009). "In contrast, after pretreatment with the caspase-2 inhibitor, the yield of LDH released was 9.3%±6.0% and 24.7%±13.3% at 8 h and 24 h post infection, respectively." (PMID 19714247, 2009). "The caspase colorimetric assay showed that caspase-2 enzyme activity of RB51 and RA1 infected macrophages increased approximately 59.9%±8.3% (p<0.05) and 55.7%±1.9% (p<0.05) respectively at 1 h post infection." (PMID 19714247, 2009). "Analysis of Casp2 protein interactions revealed that it interacted with Bcl2 during secondary but not primary infection." (PMID 25341656, 2014). "In summary, the finding that apoptotic proteins such as Casp2, Acrv1b, and Hsp90a.1 are more prominent during secondary rather than primary infection is intriguing." (PMID 25341656, 2014). "It is our new finding that the majority of infected RB51 bacteria were killed during the first 24 h in wild type DCs, followed by a slight increase of live RB51 cells at 48 h post infection, and RB51 induces caspase-2-mediated DC maturation and cytokine production." (PMID 22927979, 2012). "The inhibitor did not change the phagocytosis of RB51 by macrophage cells as demonstrated by similar number of living brucellae with or without the caspase-2 inhibition at 1 h post infection." (PMID 19714247, 2009). "Caspase-2 enzyme activation and cleavage were observed at the early infection stage in macrophages infected with RB51 and RA1 but not strain 2308." (PMID 19714247, 2009). "In this study, we demonstrated that the human tonsillar epithelial cells infected with EV-A71 underwent apoptotic, in which cytochrome c was released from the mitochondria to the cytosol and caspase-9 was activated, while caspase-2 and -8 were not cleaved or activated during the infection." (PMID 33481814, 2021).
neurodegenerative disease (8 papers, 2015 to 2024). A disorder of the central nervous system characterized by gradual and progressive loss of neural tissue and neurologic function. "Considering the involvement of caspase-2 in neuronal cell death, blocking PIDDosome formation was suggested as an effective therapeutic intervention against neurodegenerative diseases caused by excessive neuronal cell death under certain conditions." (PMID 30281648, 2018). "Abnormal regulation of caspase-2-mediated neuronal cell death causes neurodegenerative diseases and defective brain development." (PMID 30281648, 2018). "In addition to its well-defined role in cell death, Casp2 has been implicated in neurodegenerative diseases, tumorigenesis, metabolism and aging." (PMID 26687445, 2015). "Active caspase-2 cleaves aggregate-forming proteins and regulates dendritic spine density, promoting the pathogenesis of neurodegenerative diseases." (PMID 39625520, 2024). "It is possible, therefore, that in neurodegenerative diseases, caspase-2 protein redistributes to the cytosol, explaining the increases in levels we measured." (PMID 36129947, 2022). "In a mouse model, cleavage of tau by caspase-2 had a detrimental effect on cognitive function, again pointing to a link between caspase-2 and neurodegenerative diseases." (PMID 33425918, 2020). "All these studies demonstrated CASP2 may be a key factor in stemazole’s anti-apoptosis effects and ability to treat neurodegenerative diseases." (PMID 35741576, 2022). "Recent studies have reported caspase-2 dependent cell death and related neurodegenerative diseases." (PMID 30281648, 2018).
adenocarcinoma (3 papers, 2019 to 2024). A common cancer characterized by the presence of malignant glandular cells. "We chose the A549 human adenocarcinoma cell line because previous reports showed caspase-2 activation in these cells, and A549 cells have high transduction efficiency." (PMID 38248479, 2024).
metabolic disease (3 papers, 2017 to 2022). A congenital disorder (due to inherited enzyme abnormality) or acquired (due to failure of a metabolically important organ) disorder resulting from an abnormal metabolic process. "Casp2 is implicated in several diseases, including optic nerve injuries, neonatal brain damage, age-related neurodegeneration, and metabolic diseases." (PMID 36379916, 2022).
neurodevelopmental disorder (2 papers, 2024). A behavioral and cognitive disorder with onset during the developmental period that involves impaired or aberrant development of intellectual, motor, or social functions. "Interestingly, mutations in RAIDD or PIDD1 that impair caspase-2 activation cause neurodevelopmental disorders with pachygyria and psychiatric features." (PMID 38676703, 2024). "Thus, similar to biallelic CRADD and PIDD1 loss of function, we observed a mild to moderate neurodevelopmental disorder associated with biallelic CASP2 variants." (PMID 37880421, 2024).
CASP2 also shares sentences with these, for which no sentence is quoted: liver steatosis (4 papers); mantle cell lymphoma (3); cardiomyopathy (2); chronic lymphocytic leukaemia (2); diabetes (2); esophageal adenocarcinoma (2); fibrosarcoma (2); gastric cancer (2); hairy cell leukaemia (2); Intellectual disability (2); nervous system diseases (2); Parkinson disease (2); triple-negative breast carcinoma (2); acute lymphocytic leukemia (1); acute monocytic leukemia (1); adenoma (1); adrenal tumor (1); age (1); alcoholic fatty liver disease (1); blood cancer (1); breast adenocarcinoma (1); central obesity (1); colon adenocarcinoma (1); colon adenoma (1); esophageal cancer (1); fibrosis (1); heart diseases (1); Hyperinsulinemia (1); hyperthyroidism (1); hypothyroidism (1).
A further 21 diseases each share a sentence with CASP2 in 1 paper.